TAGLN (transgelin)
Diseases named in the same sentence as TAGLN in open-access papers (continued):
Sharing a sentence is not in itself a finding about the gene and the disease.
diabetes (5 papers, 2008 to 2023). "A homolog of transgelin-2, transgelin, is also highly expressed in PDAC patients with diabetes." (PMID 28521289, 2017). "In addition, our studies found that TSP1 targets included: TAGLN, a regulator of angiogenesis, LOXL4, a contributor to the vascular permeability in diabetes, types of collagen (COL4A1 and COL8A1) that influence angiogenesis plus THSB1 an inhibitor of angiogenesis." (PMID 36949528, 2023).
endometriosis (5 papers, 2019 to 2025). The growth of functional endometrial tissue in anatomic sites outside the uterine body. "TAGLN also appears to play a pivotal role in endometriosis pathogenesis as part of the signaling pathway activated by Fusobacterium nucleatum infection." (PMID 40072086, 2025). "The available literature indicates that TAGLN is significantly upregulated in ectopic endometrium compared to eutopic endometrium of endometriosis patients." (PMID 40072086, 2025). "Similarly, another study observed that TAGLN expression was significantly higher in endometriosis lesions compared to normal eutopic endometrium from endometriosis-free controls." (PMID 40072086, 2025). "Their study identified TAGLN as a specific protein expressed in peritoneal endometriotic lesions but absent in normal peritoneum, highlighting its potential role in the pathogenesis of endometriosis." (PMID 40072086, 2025). "It is thus extremely important to explore in future studies whether the TGF-β1/TGFBI and TGF-β1/TAGLN signaling axes mediate and consolidate the hypoxia-driven and the inflammation-driven aspects of the endometriosis pathology." (PMID 39744178, 2024). "Importantly, in literature, TAGLN has also been investigated in the context of endometriosis, showing increased gene expression in endometriotic lesions and being upregulated by the pathogenic Fusobacterium in endometrium of endometriosis patients." (PMID 39744178, 2024). "For example, TAGLN may be involved in cell invasion, migration, and differentiation in endometriosis." (PMID 34522169, 2021). "In addition, some identified hub genes of the EC (TAGLN, GATA6, CDH3, CLU, COL8A1, MYH11, MYOCD) and EU (CXCL13, DDK-1, KLF4, CYP2E1, CYP4B1 and PROK1) have been reported be associated with endometriosis." (PMID 34522169, 2021).
Hypertension (5 papers, 2012 to 2024). The presence of chronic increased pressure in the systemic arterial system. "TAGLN with at least one causal gene was associated with Arterial Hypertension (q = 7.739x10-8) and Smooth Muscle Cell Dysfunction in Arterial Hypertension (q = 2.203x10-5)." (PMID 39480826, 2024). "TAGLN with ACTA2 was hypothetically associated with TRPM4/6/7/8 Signalling in Arterial Hypertension (Hypothesis) (q = 1.016x10-2), Smooth Muscle Cell Dysfunction in Arterial Hypertension (q = 1.334x10-2), and TGF-Beta Family in Epithelial Mesenchymal Transition in Cancer (q = 1.878x10-2)." (PMID 39480826, 2024). "We establish that over-expression of transgelin is confined, especially at early time intervals in periglomerular “activated” fibroblasts and we demonstrate that this cell type is characteristic of the UUO model and is not “activated” in the hypertension-induced renal fibrosis." (PMID 23840546, 2013).
pancreatic cancer (5 papers, 2014 to 2025). "Expression of TAGLN has been implicated with KRAS signaling in promoting proliferation in pancreatic cancer, KRAS mutations being the most frequent aberration in MOC." (PMID 36222710, 2022). "In patients with advanced pancreatic cancer, transgelin was upregulated and was an independent factor predictive of poor prognosis." (PMID 32583562, 2020). "Pancreatic cancer patients with high transgelin expression showed a shorter 5-year overall survival rate than those with low transgelin expression." (PMID 25109740, 2014). "Both prognostic genes appear to be expressed in the stroma, with upregulation of TAGLN in gastric stromal carcinoma-associated fibroblasts, and increased expression of THBS2 implicated in tumor progression and poor prognosis in pancreatic cancer, excreted by stromal fibroblasts." (PMID 36222710, 2022). "The upregulation of transgelin was observed in gastric and pancreatic cancers." (PMID 25109740, 2014).
breast tumour (3 papers, 2015 to 2023). "The average relative expression (ARE) ± standard error of means (SEM) was 0.476 ± 0.1520 for normal tissues while it was 0.146 ± 0.0511 for tumor tissues, with an average decrease in TAGLN expression of 3.255-fold in breast tumor tissues." (PMID 26421063, 2015). "This shows that TAGLN is likely to be downregulated more by promoter DNA hypermethylation in breast tumors with worse prognosis." (PMID 26421063, 2015). "Additionally, qRT-PCR and immunohistochemistry experiments showed that TAGLN expression was significantly downregulated in two more independent sets of breast tumors compared to normal tissues and was lower in tumors with poor prognosis." (PMID 26421063, 2015). "Our data from early-stage breast tumours shows that EphA3 is particularly expressed in stromal CAF populations that express genes typical of myofibroblast-like perivascular/smooth muscle cells, including SMA, Transgelin, and other genes associated with acto-myosin regulation." (PMID 37760615, 2023). "In this study, we showed strong and consistent downregulation of TAGLN mRNA and protein expression in three independent sets of breast tumor tissues compared to non-tumor tissues (total number of samples n = 130 tumors and n = 35 normal tissues)." (PMID 26421063, 2015). "Both protein (P = 0.0116) and mRNA expression levels (P = 0.0072) of TAGLN were significantly downregulated in breast tumors in comparison to non-tumor tissues." (PMID 26421063, 2015). "This suggests that downregulation of TAGLN expression may not be related to the EMT state of breast tumors while its downregulation can be an important marker in breast tumor progression." (PMID 26421063, 2015).
esophageal squamous cell carcinoma (3 papers, 2021 to 2024). Esophageal squamous cell carcinoma (ESCC) is a type of esophageal carcinoma (EC) that can affect any part of the esophagus, but is usually located in the upper or middle third. "We found that TAGLN was low expressed in esophageal squamous cell carcinoma and was associated with prognostic characteristics." (PMID 34552870, 2021). "Transgelin expression was also associated with stage, grade, and overall survival of esophageal squamous cell carcinoma." (PMID 34552870, 2021). "The authors also demonstrate that TAGLN enhances ferroptosis, thereby curtailing the aggressive development of esophageal squamous cell carcinoma." (PMID 39308508, 2024). "We found that TAGLN inhibited the proliferation, invasion and migration of esophageal squamous cell carcinoma cells by inhibiting EMT." (PMID 34552870, 2021). "Our study shows that TAGLN can inhibit the malignant progression of esophageal squamous cell carcinoma." (PMID 34552870, 2021). "In this study, Transgelin was found to be less expressed in esophageal squamous cell carcinoma tissues compared with adjacent normal tissues." (PMID 34552870, 2021). "This may also be the reason for the low expression of Transgelin in esophageal squamous cell carcinoma." (PMID 34552870, 2021). "This article investigates the role of Transgelin (TAGLN) in the epithelial–mesenchymal transition (EMT) of esophageal squamous cell carcinomas (ESCC) and its possible mechanism of inhibiting the invasion of these cancers." (PMID 34552870, 2021). "Especially, the expression pattern, function and mechanism of TAGLN in esophageal squamous cell carcinoma are not clear." (PMID 34552870, 2021). "The role of Transgelin in esophageal squamous cell carcinoma has not been reported." (PMID 34552870, 2021).
glioma (3 papers, 2017 to 2024). A benign or malignant brain and spinal cord tumor that arises from glial cells (astrocytes, oligodendrocytes, ependymal cells). "Analysis of TAGLN expression in an independent glioma database, the Chinese Glioma Genome Atlas (CGGA), revealed that GBMs showed higher TAGLN expression than low‐grade gliomas (LGG), supporting an association with tumor grade." (PMID 38087889, 2024). "To validate these findings at the protein level, we performed immunohistochemistry (IHC) for TAGLN on tissue arrays with glioma surgical specimens of various grades (grade 2 (n = 23), grade 3 (n = 13), and GBM (n = 45)) and normal brain tissues (n = 3)." (PMID 38087889, 2024). "While our study is limited by the availability of only one established heterozygous IDH1 mutant glioma cell line, the epigenetic regulation of transgelin, a homologue of TAGLN2, has been reported in multiple other cancer types." (PMID 30647847, 2018). "Our results are in agreement with a recent study that found higher levels of multiple transgelin peptides in stem cells isolated from high grade gliomas compared to low grade gliomas." (PMID 30647847, 2018). "In tMSCs isolated from low and high grade gliomas, different isoforms of mesenchymal-related proteins vimentin and transgelin were differentially expressed." (PMID 28670517, 2017). "We found that different isoforms of two proteins including vimentin and transgelin were differentially expressed in both tMSCs isolated from different gliomas." (PMID 28670517, 2017). "TAGLN co‐distributed with GSC markers CD133, CD15, SOX2, and OLIG2 in glioma cells, suggesting that TAGLN was preferentially expressed in GSCs in patient tissues." (PMID 38087889, 2024). "Using these matched cells, TAGLN was preferentially expressed in GSCs but not in matched DGCs, bulk glioma cells, or neural precursor cells (NPCs) under hypoxia." (PMID 38087889, 2024). "TAGLN was strongly expressed in glioma cells in 41 of 45 (91.1%) of GBMs, 11 of 13 (84.6%) of grade 3 gliomas, but in fewer than 30% of grade 2 gliomas, and was absent in normal brain tissues." (PMID 38087889, 2024).
invasive carcinoma (3 papers, 2018 to 2023). A carcinoma that is not confined to the epithelium, and has spread to the surrounding stroma. "Earlier study indicated that TAGLN is an SMC-lineage marker in rabbit bladders; however, TAGLN was regarded as a marker of active stromal remodeling in the vicinity of invasive carcinomas as well." (PMID 31591355, 2019). "Validation by immunohistochemistry revealed the exclusive expression of transgelin and transgelin‐2 in the stromal tissue compartment and neoplastic glandular compartment, respectively, suggesting its important role in active stromal remodelling of invasive carcinomas." (PMID 28944995, 2018).
keloid (3 papers, 2007 to 2025). An irregularly shaped, elevated mark on the skin caused by deposits of excessive amounts of collagen during wound healing. "To validate this result, we compared the expression of TAGLN in fibroblasts derived from 10 normal skin specimens, 10 hypertrophic scars, and 10 keloids by real-time quantitative PCR (RT-qPCR)." (PMID 39781462, 2025). "According to our previous single-cell sequencing results (GSE243716) 37, TAGLN is a marker gene for fibroblast subpopulations enriched in human fibrotic skin tissues, including hypertrophic scars and keloids." (PMID 39781462, 2025). "The areas of α-SMA-positive or TAGLN-positive myofibroblasts in keloid tissues were larger than those observed in mature and immature scar tissues (P < 0.001)." (PMID 38622256, 2024). "In contrast, the widely distributed α-SMA and TAGLN-positive myofibroblasts compose a thick keloid lesion." (PMID 38622256, 2024). "Our findings revealed a significantly higher ratio of KANK-positive area to the TAGLN-positive area in keloids samples compared with immature scar samples (P < 0.01)." (PMID 38622256, 2024). "Subsequently, we then verified the expression levels of these eight overlapped genes in RNA extracted from the TAGLN-positive area of keloid (n = 12) and immature scar (n = 10) samples by quantitative PCR." (PMID 38622256, 2024). "Further RNA-seq analysis, using RNA extracted from TAGLN-positive areas in keloid and immature scars, identified keloid-specific genes that showed differentially expression in these myofibroblasts." (PMID 38622256, 2024). "Immunohistochemical analysis showed that KANK4 protein was mostly expressed in TAGLN-positive myofibroblasts in keloid tissues." (PMID 38622256, 2024). "Therefore, we collected the TAGLN-positive area from three keloid samples and two immature scar samples, and performed RNA-seq." (PMID 38622256, 2024). "The expression levels of TAGLN and KANK4 tend to be higher in keloid fibroblasts (n = 10) versus immature scar fibroblasts (n = 13) (P = 0.06 and 0.06, respectively)." (PMID 38622256, 2024). "Indeed, scRNA-seq data of keloid and normal scar fibroblasts (GSE163973) showed the presence of TAGLN-positive myofibroblasts in both types of fibroblasts." (PMID 38622256, 2024). "To identify the specific characteristics of keloid myofibroblasts, we initially assessed the expression levels of well-established myofibroblast markers, α-smooth muscle actin (α-SMA) and transgelin (TAGLN), in scar and keloid tissues (n = 63 and 51, respectively)." (PMID 38622256, 2024). "The results revealed the presence of α-SMA- and TAGLN-positive areas in immature scars and keloids, but not in mature scars." (PMID 38622256, 2024). "Notably, α-SMA- and TAGLN-positive myofibroblasts were abundantly present in both normal immature scar and keloid samples." (PMID 38622256, 2024). "Interestingly, TAGLN-negative fibroblasts did not express KANK4 in keloid samples." (PMID 38622256, 2024).
osteosarcoma (3 papers, 2017 to 2022). A usually aggressive malignant bone-forming mesenchymal neoplasm, predominantly affecting adolescents and young adults. "The relative expression levels of IGFBP4, SERPINE1, ANPEP and TAGLN were significantly lower in the osteosarcoma group compared with the normal group." (PMID 35665757, 2022). "And the SVM presented that there exists strong relationship among the expression of IGFBP4, TAGLN, and osteosarcoma." (PMID 35665757, 2022). "In this study, the TAGLN gene was low expressed in osteosarcoma, and low expression had a poor prognosis, which was the same as previous studies." (PMID 35665757, 2022). "Compared with the normal group, the relative expression of IGFBP4 and TAGLN in the osteosarcoma animal model was lower (P < 0.05)." (PMID 35665757, 2022). "We also explored the clinical implications of IGFBP4 and TAGLN expression status in patients with osteosarcoma, and the animal experiment was performed to verify the role of IGFBP4 and TAGLN on the osteosarcoma." (PMID 35665757, 2022). "Support Vector Machine (SVM) was performed to construct the correlation among the expression of IGFBP4, TAGLN, and osteosarcoma." (PMID 35665757, 2022). "It was found that the IGFBP4 gene and TAGLN gene were under-expressed in osteosarcoma, and when the two genes were under-expressed, patients had a poor prognosis." (PMID 35665757, 2022). "In the current study, we evaluated the expression pattern of IGFBP4 and TAGLN in patient-derived osteosarcoma tissues." (PMID 35665757, 2022). "By the Human Protein Atlas, protein expression of IGFBP4 and TAGLN in the osteosarcoma was lower than the normal (P < 0.05)." (PMID 35665757, 2022). "Based on the qPCR and immunofluorescence, IGFBP4 and TAGLN were down-regulated in the osteosarcoma tissue than the control group." (PMID 35665757, 2022). "There existed strong value of IGFBP4 and TAGLN on the development and occurrence of osteosarcoma." (PMID 35665757, 2022). "Furthermore, predictable value of IGFBP4 and TAGLN for the osteosarcoma was found via the support vector machine (SVM)." (PMID 35665757, 2022). "This study showed that IGFBP4 and TAGLN were of low expression in patients with osteosarcoma." (PMID 35665757, 2022). "IGFBP4 and TAGLN may be attractive molecular targets for osteosarcoma, opening a new avenue for research into the disease." (PMID 35665757, 2022). "Through bioinformatics, IGFBP4 and TAGLN were identified as the hub genes of osteosarcoma." (PMID 35665757, 2022). "TAGLN was upregulated in osteosarcoma cell lines and tumor tissue." (PMID 28968955, 2017). "Finally, IGFBP4 and TAGLN may be attractive molecular targets for osteosarcoma, opening a new avenue for research into the disease." (PMID 35665757, 2022). "However, effect of IGFBP4 and TAGLN on the survival of osteosarcoma is unclear." (PMID 35665757, 2022). "And osteosarcoma patients with high expression levels of IGFBP4 (HR = 0.56, P = 0.013) and TAGLN (HR = 0.52, P = 0.012) had better overall survival times than those with low expression levels." (PMID 35665757, 2022). "Osteosarcoma patients with high expression levels of IGFBP4 (HR = 0.56, P = 0.013) and TAGLN (HR = 0.52, P = 0.012) had better general survival times than those with low expression levels." (PMID 35665757, 2022). "And LYN, TNC, TGFB2, IGFBP1were up-regulated in the osteosarcoma tissue samples, while IGFBP4, TAGLN, SERPINE1, ANPEP were down-regulated." (PMID 35665757, 2022). "However, the molecular mechanism of IGFBP4 and TAGLN on osteosarcoma has not been further explored in these studies." (PMID 35665757, 2022).
prostate tumour (3 papers, 2012 to 2017). "Further studies are required to clearly identify the biological role of TAGLN in the prostate tumour stromal microenvironment, particularly in the promotion of CAF differentiation." (PMID 28510269, 2017).
renal carcinoma (3 papers, 2013 to 2022). A carcinoma arising from the epithelium of the renal parenchyma or the renal pelvis. "Furthermore, the TAGLN protein is one of the two tumor-associated antigens which were identified in serum of kidney carcinoma patients by Klade using 2-DE." (PMID 23510049, 2013). "PPP1R14A and TAGLN exhibit high and extensive synchronization in a variety of malignant tumors, especially renal carcinomas, implying that the two molecules are likely to work together, to indicate tumorigenesis." (PMID 35656324, 2022).
renal cell carcinoma (3 papers, 2021 to 2023). "It was found that TAGLN expression was significantly reduced in bladder, breast, and renal cell carcinoma tissues compared with matched normal tissues." (PMID 34552870, 2021).
sarcoma (3 papers, 2012 to 2021). A usually aggressive malignant neoplasm of the soft tissue or bone. "RST/Myo hybrids express desmin and transgelin, so the resulting tumours are classified as undifferentiated pleomorphic sarcomas with an incomplete muscular differentiation." (PMID 33303824, 2020).
Ureteral obstruction (3 papers, 2013 to 2024). Obstruction of the flow of urine through the ureter. "Transgelin expression in kidney tissue gradually increased from intermediate to advanced fibrosis stages in 5/6 Nx rats and mice with unilateral ureteral obstruction." (PMID 39375532, 2024). "In this report, using the unilateral ureteric obstruction model for renal fibrosis in rodents, we focus on the expression of transgelin." (PMID 23840546, 2013). "Proteomic analysis of the renal parenchyma in the well-established rat model of unilateral ureteral obstruction (UUO model) suggested that transgelin was up-regulated during the development of fibrosis." (PMID 23840546, 2013). "In a unilateral ureteric obstruction model, transgelin expression was also induced early." (PMID 32583562, 2020).
bladder tumor (2 papers, 2019 to 2023). "qRT-PCR demonstrated that the mRNA expression levels of ACTA2, FLNA, TAGLN, and TPM1 in bladder tumor cells were significantly decreased compared with normal bladder cells, which corresponded to the results of our prior bioinformatic investigation using public datasets." (PMID 37274283, 2023). "In addition, qRT-PCR and Western blotting demonstrated that the transcription and translation levels of ACTA2, FLNA, TAGLN, and TPM1 were much lower in bladder tumor cells than in normal bladder cells." (PMID 37274283, 2023).